TXLNG (taxilin gamma)
Description:
May be involved in intracellular vesicle traffic. Inhibits ATF4-mediated transcription, possibly by dimerizing with ATF4 to form inactive dimers that cannot bind DNA. May be involved in regulating bone mass density through an ATF4-dependent pathway. May be involved in cell cycle progression.
Synonyms: FIAT; CXorf15; ELRG; LSR5; FLJ11209; MGC126621; MGC126625; TXLNGX
Tractability: PROTAC: ubiquitination databases record sites on it; its protein half-life has been measured.
Gene: Protein-coding gene on chromosome X (16,786,432 to 16,844,519, forward strand). Ensembl gene ENSG00000086712.
Subcellular location: Nucleus membrane; Cytoplasm, cytosol
Subcellular location (Human Protein Atlas): Cytosol
Gene Ontology:
Molecular function: DNA-binding transcription factor binding
Biological process: regulation of cell cycle process; regulation of bone mineralization; regulation of cell cycle
Cellular component: nuclear membrane; cytosol
Homologues: Orthologues: chimpanzee TXLNG (98% identical), macaque TXLNG (98% identical), rabbit TXLNG (92% identical), mouse Txlng (90% identical), rat Txlng (90% identical), guinea pig TXLNG (89% identical), zebrafish txlng (56% identical), Drosophila melanogaster CG5886 (24% identical), tropical clawed frog txlng (20% identical), Caenorhabditis elegans T22C1.6 (18% identical). Paralogues in human: TXLNA (51% identical), TXLNB (43% identical).
Diseases named in the same sentence as TXLNG in open-access papers:
TXLNG is named in the same sentence as 5 diseases in open-access papers, as found by Europe PMC text mining. Sharing a sentence is not in itself a finding about the gene and the disease. The quoted sentences say what the papers report.
osteoporosis (1 paper, 2018). A condition of reduced bone mass, with decreased cortical thickness and a decrease in the number and size of the trabeculae of cancellous bone (but normal chemical composition), resulting in increased fracture incidence. "TXLNG may regulate bone mass density and is an interesting candidate gene of the decreased bone mass and the increased risk of developing osteoporosis in KS." (PMID 30213969, 2018).
cancer (2 papers, 2020 to 2022). A tumor composed of atypical neoplastic, often pleomorphic cells that invade other tissues. "Particularly, expressions of ZFX and TXLNG were both positively correlated with XIST in over 10 cancers." (PMID 36212008, 2022). "Of note, USP9X (log2FC/FDR = −0.31/1.7e-06), a previously reported cancer driver, TXLNG (−0.54/3.3e-17), OFD1, MED14, and CDK16 are known to evade X-inactivation and were over-expressed in females’ GC." (PMID 32849808, 2020).
TXLNG also shares sentences with these, for which no sentence is quoted: hematologic malignancies (1 paper); lung carcinoma (1); tumor (1).